GABRA1 (gamma-aminobutyric acid type A receptor subunit alpha1)
Diseases named in the same sentence as GABRA1 in open-access papers (continued):
Sharing a sentence is not in itself a finding about the gene and the disease.
GABRA1 also shares sentences with these, for which no sentence is quoted: developmental and epileptic encephalopathy (4 papers); neurodevelopmental disorder (3); Ohtahara syndrome (3); alcoholism (2); atypical Rett syndrome (2); encephalopathies (2); febrile seizures (2); Intellectual disability (2); Williams-Beuren syndrome (2); Angelman syndrome (1); bipolar disorder (1); brain tumors (1); childhood-onset epileptic encephalopathy (1); cognitive decline (1); complex partial seizures (1); cyst (1); Doose syndrome (1); Epileptic spasm (1); genetic generalized epilepsy (1); hypertrophic cardiomyopathy (1); Hypotonia (1); Hypsarrhythmia (1); infantile epileptic encephalopathy (1); legionellosis (1); leukodystrophy (1); liver fibrosis (1); Macrocephaly (1); malaria (1); microcephaly (1); mood disorder (1).
A further 10 diseases each share a sentence with GABRA1 in 1 paper.